ACHE (acetylcholinesterase (Yt blood group))
Diseases named in the same sentence as ACHE in open-access papers (continued):
Sharing a sentence is not in itself a finding about the gene and the disease.
metabolic syndrome (10 papers, 2015 to 2024). A cluster of metabolic risk factors for CARDIOVASCULAR DISEASES and TYPE 2 DIABETES MELLITUS. "When compared to the naïve control, metabolic syndrome rats showed significant elevations in AChE, MAO, and GABA-T in the cerebral cortex and hippocampus (p-value < 0.001 all; compared to naïve control)." (PMID 36358575, 2022). "It was shown that metabolic syndrome rats increased levels of AChE in the cerebral cortex and hippocampus." (PMID 36358575, 2022). "The elevations in AChE in the cerebral cortex and hippocampus of metabolic syndrome rats were mitigated by donepezil and vitamin C (p-value < 0.001 all; p-value < 0.05 and 0.001; compared to the HFHC + vehicle group)." (PMID 36358575, 2022). "Galantamine, another AChE inhibitor, decreases inflammation and has been shown to be effective in animal models of endotoxemia, inflammatory bowel disease, lupus, and metabolic syndrome in humans." (PMID 36425123, 2022). "Centrally acting cholinergic drugs such as the acetylcholinesterase (AChE) inhibitor galantamine alleviate inflammation in preclinical settings of endotoxemia, inflammatory bowel disease, lupus, metabolic syndrome and other disorders." (PMID 34017249, 2021). "MCAO significantly enhanced AChE activity in the hippocampus of metabolic syndrome rats induced by a HCHF diet which received vehicle (P value < 0.001, compared to the HCHF+sham operation+vehicle group)." (PMID 30937145, 2019). "Bearing that in mind, we have decided to estimate cholinesterase activities in blood of children with metabolic syndrome and compared these effects with changes in AChE and BChE activities in children supplemented with A. melanocarpa extract." (PMID 29780825, 2018). "In addition, our data also showed that OA suppressed AChE in the hippocampus of metabolic syndrome rats." (PMID 30937145, 2019). "In conclusion, nonalcoholic steatohepatitis with its health complications including dyslipidemia, cholesterol impairments, oxidative stress, and upregulation of AChE with amyloid precursor protein (APP) are considered potential dangerous risk factors for neurotoxicity." (PMID 26576191, 2015).
organophosphate poisoning (10 papers, 2015 to 2025). Poisoning due to organophosphates (a class of organophosphorus compounds also known as phosphate esters, or OPEs). "These oxon metabolites are extremely potent AChE inhibitors, leading to the accumulation of the neurotransmitter acetylcholine causing the characteristic neurotoxic effects associated with organophosphate poisoning." (PMID 40964366, 2025). "Organophosphate poisoning is caused by the inhibition of acetylcholinesterase (AChE) due to the formation of a covalent enzyme–inhibitor complex, leading to an increase in acetylcholine (ACh) levels and excessive activation of nicotinic and muscarinic ACh receptors." (PMID 25692018, 2015). "Furthermore, the recovery of cholinesterase following organophosphate poisoning varies distinctively, with blood acetylcholinesterase (BChE) activity recovering considerably with a faster recovery of AChE activity." (PMID 32156097, 2020). "Restoration of the additional 10% AChE activity may influence potential sequelae, especially the neuropsychiatric and neurological impairments (memory, cognitive, mental, emotional, motor, and sensory), as described in survivors of organophosphate poisoning." (PMID 33114215, 2020). "The use of AChE reactivators is crucial in organophosphate poisoning, as atropine is not effective at the neuromuscular synapse." (PMID 41040822, 2025). "Inhibition of the enzyme, as induced by α-MG, is typically encountered following organophosphate poisoning, but alterations in RBC morphology, as seen in anemic states, may also influence AChE activity since AChE is anchored to the RBC membrane." (PMID 37764276, 2023).
breast carcinoma (9 papers, 2012 to 2024). "Tumors in which mutations in the ACHE gene were most frequently found include ductal, lobular, and tubular breast carcinoma, in which deletions predominate (65.7%) over amplifications (22.9%)." (PMID 37760598, 2023). "We evaluated their potential against two targets viz., inhibition of MDA-MB-231, and MCF-7 breast cancer cells viability and inhibition of AChE/BuChE." (PMID 37242458, 2023). "Regarding this phenomenon in breast cancer, Dr. Garrido’s group demonstrated in the rat mammary gland that inhibition of AChE with physostigmine (eserine) induced carcinogenesis, showing a relationship between the decrease in AChE activity and carcinogenesis." (PMID 37760598, 2023). "Similarly, Boberg and collaborators found amplification in 62.5% of the sporadic breast cancer samples analyzed, making clear the relationship between the modification in the ACHE gene and the development of tumors." (PMID 37760598, 2023). "In addition, some works report alterations in the ACHE gene, such as in breast cancer; these alterations decreased the enzymatic activity in axillary lymph nodes, which was heightened as the malignancy of the tumors progresses." (PMID 37760598, 2023). "This would suggest that inhibition of AChE would promote cell proliferation and tumorigenesis, an effect that could be demonstrated through the use of AChE inhibitor eserine in a rat model of breast cancer." (PMID 34500749, 2021). "“Tumor size was significantly higher when the ACHE gene was amplified in breast cancer.”." (PMID 23216862, 2012). "Results of hH3R radioligand displacement assays; ex vivo histamine gpH3R, gpH1R screening on the isolated guinea pig ileum; inhibition of electric eel AChE and equine serum BuChE; MTT test results after 48 h treatment of MDA-MB-231 and MCF-7 breast cancer cells." (PMID 37242458, 2023). "For example, the indirect-type probe HBTP can recognize Cu2+ and AChE successively and has been applied to human embryonic kidney cells HEK293, and the probe NFL-SF can recognize AChE and has been applied to human cervical cancer cells (HeLa) and human breast cancer cells (MCF-7)." (PMID 38731452, 2024). "On the other hand, no changes were found in lung squamous cell carcinoma and breast cancer, indicating that AChE expression could not have a relevant role in these tumors." (PMID 37760598, 2023).
liver cancer (9 papers, 2014 to 2025). An epithelial or non-epithelial malignant neoplasm that arises from the liver. "AChE can degrade the ACh and reduce the malignant development risk of liver cancer, thus AChE has been identified as a prognostic marker in liver cancer." (PMID 33482834, 2021). "Our study revealed liver cancer within the severely impaired subgroup of tumors with a mean (AChE) activity of 16.5 ± 7.4." (PMID 38429330, 2024). "Wang and co-workers developed transferrin-modified liposomes (Tf-PL) for the targeted delivery of acetylcholinesterase (AChE) gene, administered subcutaneously to treat liver cancer xenografts grafted in nude mice." (PMID 35822814, 2022). "We found that the derived Tf-PL/AChE liposomes exhibited much higher transfection efficiency than the commercial product Lipo 2000 and shown premium targeting efficacy to liver cancer SMMC-7721 cells in vitro." (PMID 33482834, 2021). "Oncomine database shows extremely high expression of ACh in various tumor tissues including liver cancer, p = 0.002, while AChE shows significant low expression in liver cancer p = 0.012." (PMID 33482834, 2021). "Herein, we prepared transferrin-modified liposomes (Tf-PL) for the targeted delivery of acetylcholinesterase (AChE) therapeutic gene to liver cancer." (PMID 33482834, 2021). "In conclusion, the strategy of combining the transferrin liposome and AChE gene provides a new idea for gene therapy of liver cancer." (PMID 33482834, 2021). "In this work, we put forward a strategy for the delivery of the AChE gene by the transferrin modified liposome targeting TfR on the surface of liver cancer cells for liver cancer therapy." (PMID 33482834, 2021). "In this study, using liver cancer cell lines expressing different amounts of ACHE/BCHE and epithelial or mesenchymal characters, we established a novel xenograft model in wild-type and ache mutant zebrafish larvae at 3 dpi." (PMID 29371671, 2018). "Next, we studied AChE/BChE enzymatic activity in our panel of liver cancer cell lines using a modified Ellman method based assay." (PMID 29371671, 2018). "First, we characterized six different liver cancer cell lines in terms of their acetylcholinesterase/butyrylcholinesterase (ACHE/BCHE) expression and activity." (PMID 29371671, 2018). "Acetylcholinesterase (AChE), an enzyme responsible for degradation of acetylcholine, has been identified as a prognostic marker in liver cancer." (PMID 29371671, 2018). "The correlation of AChE expression and prognosis in gastric cancer patients is similar to liver cancer." (PMID 25220382, 2014). "Lower level of AChE in cancer tissues and the reverse correlation of AChE expression with survival time were reported in liver cancer patients." (PMID 25220382, 2014). "Ad.AChE also decreased cell viability in other digestive system cancers, including liver cancer cell line (Huh-7 and SMMC-7721), colon cancer cell line (SW480) and pancreatic cancer cell line (BxPc-3)." (PMID 25220382, 2014). "Furthermore, the subcutaneous injection of Tf-PL/AChE significantly inhibited the growth of liver cancer xenografts in nude mice." (PMID 38794336, 2024). "In vivo, the Tf-PL/AChE could effectively target liver cancer, and significantly inhibit the growth of liver cancer xenografts grafted in nude mice by subcutaneous administration." (PMID 33482834, 2021). "Furthermore, ectopic expression of the AChE gene can significantly inhibit the proliferation of liver cancer cells in xenograft model." (PMID 33482834, 2021). "However, currently there is no in vivo xenograft model for evaluating the connection between AChE and liver cancer development and progression in zebrafish." (PMID 29371671, 2018). "Therefore, AChE can be used as a gene therapy target for liver cancer." (PMID 33482834, 2021). "The system had a high % encapsulation efficiency of 94.3%, induced apoptosis, and arrested cell cycles, highlighting Tf-PL/AChE as a promising non-viral gene delivery platform for targeted liver cancer therapy." (PMID 40321406, 2025).
malaria (9 papers, 2006 to 2022). Malaria is a serious and sometimes fatal disease caused by a parasite that commonly infects a certain type of mosquito which feeds on humans. "Copper is mentioned in a study concerned with the development of AChE inhibitors instead of pyrethroid insecticides to control Anopheles gambiae mosquito; a vector of malaria-causing Plasmodium." (PMID 36555061, 2022). "As shown in Fig. (9A), 6 μM AMTS13 causes rapid irreversible inhibition of African malaria mosquito AChE achieving 50% irreversible inhibition within 10 minutes." (PMID 22280344, 2012). "Of mechanistic importance, 6 μM AMTS13 causes rapid and irreversible inhibition of African malaria mosquito AChE, reaching ~50 and ~100% irreversible inhibition within 10 and 30 minutes, respectively." (PMID 22280344, 2012). "Acetylcholinesterase (AChE) is a validated target in the insect nervous system and inhibitors of this critical enzyme have been useful in the control of malaria vectors for over eighty years." (PMID 36296618, 2022). "In this study, previously identified derivatives of a potent AChE, donepezil, that have exhibited low activity on electric eel AChE were assessed for potential AChE-based larvicidal effects on four African malaria vectors; An." (PMID 36350894, 2022). "Synaptic acetylcholinesterase (AChE) is an essential neurotransmission enzyme targeted by insecticides used increasingly in malaria control." (PMID 25865270, 2015). "The fast, nearly complete, and irreversible inhibition of African malaria mosquito AChE by 6 μM AMTS13 is initiated by a reversible interaction between the ammonium group of AMTS13 and Trp84 placing the methanethiosulfonate group at the rim of the active site." (PMID 22280344, 2012). "These inhibitors also show 95% inhibition of the total AChE activity in the African malaria mosquito and >80% inhibition in northern house and the yellow fever mosquitoes." (PMID 22280344, 2012). "Under conditions that spare hAChE, low-concentration AMTS17 is able to quickly, selectively, and irreversibly inhibit most of total AChE activity extracted from mosquitoes that transmit malaria, dengue, yellow fever, chikungunya, or St." (PMID 19714254, 2009). "The two residues are conserved also in the African malaria-carrying mosquito AChE mutant that is resistant to current pesticides." (PMID 17183688, 2006). "While a three-dimensional (3D) model of African malaria-carrying mosquito (Anopheles gambiae) AChE (AgAChE) has been reported, no conserved and mosquito-specific region of AgAChE has been reported until now." (PMID 17183688, 2006).
Senile plaques (9 papers, 2010 to 2024). Senile plaques are extracellular deposits of amyloid in the gray matter of the brain. "AChE is an enzyme involved in diverse functions in both central and peripheral nervous systems and it has been demonstrated to be associated with senile plaques." (PMID 20205793, 2010). "These pathological symptoms were similar to other reports showing that intracisternal injection of Aβ 1-42 over 2 weeks causes Aβ deposition in rat brain using immunohistochemical stain, and then causes an up-regulation in AChE activity within and around senile plaques." (PMID 24968859, 2014). "In the brain of people with AD, AChE is localized in amyloid deposits and the mature senile plaques (Morán and Mufson 1993)." (PMID 37598127, 2023). "The diffuse deposition of Aβ together with AChE is particularly interesting since it represents an early step in the development of senile plaques." (PMID 38003588, 2023). "On the other hand, studies have shown that cholinesterase, as one of the components of senile plaques, stimulate the assembly of amyloid fibers and combine with them to format highly toxic Aβ–AChE complexes which have a neurotoxic effect higher than that of both alone." (PMID 35996073, 2022). "Most of the cortical AChE activity present in AD brain is predominantly associated to the amyloid core of senile plaques rather than with the neuritic component found in the periphery." (PMID 20205793, 2010).
colon carcinoma (8 papers, 2008 to 2025). "On the other hand, Dr. Weber’s group has shown that in colon cancer, there is an increase in the AChE activity and the binding of c-Myb to DNA accompanied by the cell adhesion; they showed that AChE influences intracellular signal transduction." (PMID 37760598, 2023). "The previous characterization of LPE has demonstrated that it shows antioxidant properties, anti-inflammatory and chemo-preventive activity in human gastric and colon cancer cells and inhibits in vitro AChE activity." (PMID 37687161, 2023). "In colon cancer patients, Dr. Vidal’s group demonstrated that several molecular forms of AChE were present in healthy colon tissues: G1A, G2A, G2H, G4A, G4H, and A4." (PMID 37760598, 2023). "These ACHE exons also appeared in exon array data sets from colon cancer and multiple healthy tissues." (PMID 18545673, 2008). "Furthermore, abnormal expression and structural alteration of AChE and multiple activities have been found in different types of tumors, such as brain, lung, ovarian, breast, hepatocellular, renal, and colon cancers, which indicate the involvement of AChE in regulating the tumor development." (PMID 26932526, 2016). "Here, immunoblot analysis of commonly used human PCC lines, T3M-4, SU.86.86 and Panc-1, as well as colon carcinoma cell lines SW620 and DLD-1, and the glioblastoma cell line LN229, revealed high levels of AChE expression when compared to DRG of C57BL/6 J mice." (PMID 33357230, 2020).
Insulin resistance (8 papers, 2013 to 2024). Increased resistance towards insulin, that is, diminished effectiveness of insulin in reducing blood glucose levels. "DM decreases the acetylcholinesterase (AChE) activity on brain or erythrocytes membrane, which is a potential cause of insulin resistance." (PMID 28531120, 2017). "Our promising results of alkaloid berberine treatment showed its potential therapeutic activity against the NASH and its associated diseases such as insulin resistance and Alzheimer-like pathology via its effect as antioxidant, anti-inflammatory, an AChE inhibitor and HMG-CoA reductase inhibitor." (PMID 26576191, 2015). "The results showed that pyridostigmine decreased AChE activity, increased ACh levels in serum and in gut and cardiac tissues, and exerted beneficial effects on insulin resistance and cardiac damage in diabetic cardiomyopathy mice." (PMID 34084135, 2021). "Animals in fructose-drinking insulin resistance group showed significantly higher AChE activity in the hippocampus and cerebral cortex than control rats (P<0.01, P<0.05)." (PMID 23527159, 2013). "Reduced AChE activity in both brain regions in pioglitazone-treated fructose-drinking insulin resistance rats were observed compared with fructose-drinking insulin resistance rats (P<0.01, P<0.05)." (PMID 23527159, 2013). "In our previous studies, we showed that fructose-drinking insulin resistance promotes Aβ-amyloidosis in the brain, and AChE activity is increased within and around amyloid plaques." (PMID 23527159, 2013). "We found an increased AChE activity and decreased ACh level in fructose-drinking insulin resistance rats in the present study." (PMID 23527159, 2013). "This is consistent with a previous study that AChE activity was decreased in some of the brain regions in streptozotocin-intracerebroventricularly treated central insulin resistance rats." (PMID 23527159, 2013). "Obesity and/or poor diet may lead to cognitive dysfunction via insulin resistance, which has been shown to increase acetylcholinesterase (AChE) activity and reduce synaptic levels of acetylcholine (ACh)." (PMID 37371407, 2023). "The decreased ACh level in the brains of fructose-drinking insulin resistance rats may simply result from the increased AChE activity." (PMID 23527159, 2013). "AChE was over-expressed in response to various oxidative stresses such as free radical and oxidative stress in the brain, thus it is possible that the significant increase of AChE activity in the present study is due to oxidative damage induced by insulin resistance." (PMID 23527159, 2013).
neuropathy (8 papers, 2017 to 2022). A disorder affecting the nervous system that manifests with pain, tingling, numbness, and/or muscle weakness. "All pesticides inhibited acetylcholinesterase (AChE) and neuropathy target esterase (NTE) in each of the brain regions, but esterase inhibition was greatest in the HC and CS." (PMID 35892416, 2022). "OPs affect the nervous system by inhibiting acetylcholinesterase (AChE) and other types of esterases, such as neuropathy target esterase, eliciting OP-induced delayed neuropathy syndrome." (PMID 36185539, 2022). "As neuropathic OPs must inhibit NTE ≥ 70% for at least 24 h to induce delayed neuropathy in susceptible species, the time-course inhibition of both PV-NTE and AChE activities induced by 150 mg/kg bw CBDP (MTD) was analyzed." (PMID 29555973, 2018). "In addition to AchE suppression, other evidence proposed that excessive production of ROS and lipid peroxidation (LPO) are other mechanisms implicated in CPF-induced neuropathy." (PMID 34577640, 2021). "Different from the acute toxicity that mainly stems from the inhibition of AchE, the mechanism underlying the delayed neuropathy remains unclear and no treatment is available." (PMID 28894590, 2017).